ADORA1 (adenosine A1 receptor)
Diseases named in the same sentence as ADORA1 in open-access papers (continued):
Sharing a sentence is not in itself a finding about the gene and the disease.
glioma (4 papers, 2017 to 2025). A benign or malignant brain and spinal cord tumor that arises from glial cells (astrocytes, oligodendrocytes, ependymal cells). "According to our research, excessive ADORA1 expression significantly facilitated the growth, movement, and infiltration of glioma cells, which are associated with the progression of glioma." (PMID 40376586, 2025). "ADORA1 inhibition enhanced T cell recruitment and increased glioma susceptibility to anti-PD1 therapy." (PMID 40376586, 2025). "Survival analysis of patients with glioma from TCGA database stratified into high- and low-risk groups revealed that those with elevated ADORA1 expression had a worse prognosis." (PMID 40376586, 2025). "The previous studies showed that a low level of adenosine A1 receptor/adenosine A2a receptor expression, which was observed in low-grade gliomas, could increase susceptibility to tumor-related epilepsy." (PMID 29212163, 2017). "Nevertheless, the precise impact of ADORA1 on glioma progression and its influence on anti-programmed death receptor 1 (PD1) therapy, along with the underlying regulatory mechanisms, remain to be fully elucidated." (PMID 40376586, 2025). "The immunohistochemical analysis revealed an increase in the proportion of ki67-positive cells in glioma tissues within the ADORA1 overexpression group, while the ki67 positivity rate diminished following KNG1 overexpression." (PMID 40376586, 2025). "The results of the migration and invasion assays demonstrated that elevated ADORA1 expression significantly enhanced glioma cell motility, whereas reduced ADORA1 expression markedly diminished cell movement." (PMID 40376586, 2025). "Our findings indicate that ADORA1 overexpression facilitated glioma growth and decreased survival time in the mice, whereas KNG1 overexpression mitigated these effects." (PMID 40376586, 2025). "In vivo, we conducted additional research on the molecular mechanism of ADORA1 in suppressing glioma apoptosis." (PMID 40376586, 2025). "The findings indicate that ADORA1 suppresses the expression of KNG1 in glioma, consequently impeding the anti-tumor immune response within the tumor microenvironment." (PMID 40376586, 2025). "Subsequent CD31 immunofluorescence staining indicated an enhancement in vascular density in glioma tissues post-ADORA1 overexpression; however, a reduction in vascular abundance was observed when both ADORA1 and KNG1 were overexpressed concurrently." (PMID 40376586, 2025). "ADORA1 suppresses the expression of KNG1 in glioma, consequently impeding the anti-tumor immune response within the tumor microenvironment." (PMID 40376586, 2025). "The inhibition of ADORA1 greatly enhanced the effectiveness of PD1 monoclonal antibodies in treating glioma, resulting in a notable decrease in tumor size and an extended period of survival." (PMID 40376586, 2025). "To explore the mechanism of ADORA1 in glioma progression, we searched the STRING database for potential interacting molecules." (PMID 40376586, 2025). "According to these findings, GBM exhibited a higher ADORA1 expression level than other types of glioma, and there was a positive correlation between ADORA1 and the grade of glioma." (PMID 40376586, 2025). "Our findings indicate that inhibiting ADORA1 can induce apoptosis in glioma cells and increase their sensitivity to anti-PD1 therapy." (PMID 40376586, 2025). "Previous studies have reported that ADORA1 was highly expressed in high-grade gliomas, however, the effect of ADORA1 on glioma progression and glioma immunity therapy was unclear." (PMID 40376586, 2025). "The effects of ADORA1 on glioma and anti-PD1 therapy were investigated in both laboratory settings and living organisms." (PMID 40376586, 2025). "The results of the clone formation assay showed that ADORA1 overexpression markedly enhanced the proliferation of glioma cells, whereas the opposite results were observed in the LV-shADORA1 group." (PMID 40376586, 2025).
glioma (continued). "Our results indicated that ADORA1 was highly expressed in gliomas and that ADORA1 overexpression promoted glioma progression by inhibiting KNG1." (PMID 40376586, 2025). "The results revealed a significant increase in ADORA1 expression in glioma, which was correlated with poor prognosis." (PMID 40376586, 2025). "TCGA and GTEx databases, which have more than 1800 samples, were selected and showed that the gene expression of ADORA1 was significantly higher in gliomas than in normal tissues." (PMID 40376586, 2025). "The objective of this study was to examine the influence of ADORA1 on the progression of glioma and its possible consequences for anti-PD1 treatment." (PMID 40376586, 2025). "We analyzed ADORA1 expression levels using the CGGA database to investigate the impact of ADORA1 expression on glioma progression." (PMID 40376586, 2025). "In addition, we confirmed that the expression level of ADORA1 in gliomas was significantly up-regulated by western blotting and IHC staining." (PMID 40376586, 2025). "Our study further demonstrated that ADORA1 inhibition promoted glioma apoptosis induced by KNG1." (PMID 40376586, 2025). "Our assy examined the effect of ADORA1 on the immune milieu of glioma." (PMID 40376586, 2025). "ADORA1 may serve as a prognostic marker for glioma and a potential target to enhance the effectiveness of anti-PD-1 therapy." (PMID 40376586, 2025). "Bioinformatics was used to explore the correlation between ADORA1 expression and glioma prognosis." (PMID 40376586, 2025). "This indicates that ADORA1 inhibition increased the responsiveness of glioma to anti-PD1 treatment." (PMID 40376586, 2025). "We further demonstrated that ADORA1 induces glioma progression by inhibiting KNG1." (PMID 40376586, 2025). "Previous studies have indicated high ADORA1 expression in high-grade gliomas; however, its specific role in glioma progression and the efficacy of glioma immunity therapy remain unclear." (PMID 40376586, 2025). "Furthermore, ADORA1 inhibition facilitated glioma apoptosis by augmenting kininogen-1 (KNG1)." (PMID 40376586, 2025). "Western blot analysis revealed that elevated ADORA1 expression reduced KNG1 expression in GBM-Z1 and U87 glioma cells." (PMID 40376586, 2025). "Therefore, ADORA1 inhibition might exert therapeutic effects against glioma." (PMID 40376586, 2025). "To investigate the impact of ADORA1 and KNG1 on glioma proliferation, we developed an in-situ glioma model using GL261 cells implanted in C57 mice." (PMID 40376586, 2025). "The results indicated that inhibiting ADORA1 increased the recruitment of CD8+ and CD4+ T cells in gliomas, thereby benefiting from PD-L1-targeted immunotherapy." (PMID 40376586, 2025). "We demonstrated the effect of ADORA1 on T cells, showing that inhibition of ADORA1 in the shADORA1 group increased the recruitment of CD4+ T and CD8+ T cells to gliomas compared to the control group." (PMID 40376586, 2025). "Inhibiting ADORA1 promoted glioma cell death via KNG1, increased T-cell recruitment, and improved glioma responsiveness to anti-PD1 therapy." (PMID 40376586, 2025). "To explore the role of ADORA1 in glioma, we transfected GBM-Z1 glioma cells with lentivirus (LV)-control, LV-ADORA1, or LV-shADORA1." (PMID 40376586, 2025). "In gliomas lacking IDH1/2 mutations and 1p/19q co-deletion, elevated ADORA1 expression was observed, suggesting a negative correlation with prognosis." (PMID 40376586, 2025). "Glioblastomas also demonstrate higher levels of multiple adenosine receptors (ADORA1/A1R, ADORA3/A3R) compared to all other cancer subtypes, suggesting that gliomas may have particularly active purinergic signaling, and therefore represent an attractive target for anti-CD73 therapy." (PMID 35973991, 2022). "The results revealed a negative correlation between ADORA1 expression and CD8+ T-cell presence in glioma." (PMID 40376586, 2025).
Hypertension (4 papers, 2011 to 2020). The presence of chronic increased pressure in the systemic arterial system. "In the vasculature, studies on the role of endothelium in hypertension have raised the possibility that the main mechanism regulating extracellular adenosine levels is related with adenosine uptake to endothelial cells, thus, causing a subsequent impairment of adenosine A1 receptor activation." (PMID 28481238, 2017). "In vascular tissues, recent studies concerning the role of endothelium in hypertension, had suggested that the main mechanism regulating extracellular adenosine levels involves nucleoside uptake to endothelial cells with the subsequent impairment of adenosine A1 receptor activation." (PMID 28481238, 2017). "The differential up-regulation of PTGDS and ADORA1 suggests a possible cardioprotective role of EAT toward CAD, hypertension, and other cardiovascular dysfunctions." (PMID 21603615, 2011).
Stroke (4 papers, 2019 to 2024). Sudden impairment of blood flow to a part of the brain due to occlusion or rupture of an artery to the brain. "In a recent animal study, agonism of the adenosine A1 receptor resulted in decreased microglia activation and proliferation post-stroke, which suggests that the adenosine A1 receptor could play a role in curbing neuroinflammation and preventing infarction." (PMID 41541584, 2022). "Adenosine A1 receptor (A1R) activation could ameliorate ischemic injury, representing a very tempting target for stroke treatment." (PMID 34356346, 2021).
Alzheimer disease (3 papers, 2013 to 2024). A progressive, neurodegenerative disease characterized by loss of function and death of nerve cells in several areas of the brain leading to loss of cognitive function such as memory and language. "Upregulation of genes included those involved with apoptosis (Ntn1, Adora1, and Ache) and Alzheimer’s disease (ApoE, Apbb1)." (PMID 24019935, 2013). "However, ADORA1 plays an important role as a neuroprotective molecule in the central nervous system and its activation is a common target for drugs that treat neurodegenerative diseases (such as Alzheimer's disease and multiple sclerosis)." (PMID 26185765, 2015).
diabetes (3 papers, 2019 to 2022). "In our study, SHR with STZ-induced diabetes had a markedly higher expression of the adenosine A1 receptor in the DG when compared to the control SHR group." (PMID 31150459, 2019). "Specific inhibition of ADORA1 in the liver helps prevent body weight gain and alleviate hepatic steatosis, suggesting that ADORA1 might be a promising drug target for treating diabetes and obesity." (PMID 36278175, 2022). "Therefore, diabetes-associated targets (AKT1 and PPARγ) and two targets involved in regulating glucolipid metabolism (GSK3β and ADORA1), which have the lowest free energy binding with their compounds, were selected for molecular docking and refined by exploring the specific binding sites." (PMID 36278175, 2022).
gastric cancer (3 papers, 2015 to 2023). A primary or metastatic malignant neoplasm involving the stomach. "N-3 PUFAs was also demonstrated to exert an anti-cancer effect on gastric cancer by inducing apoptosis of gastric cancer cells via ADORA1." (PMID 26402223, 2015). "Furthermore, it has been demonstrated, that EPA causes upregulation of pro-apoptotic proteins like Bax, Bak, and Adenosine A1 Receptor (ADORA1), which is a subtype of adenosine receptor functionally involved in cell death on gastric cancer cells." (PMID 37511450, 2023).
glioblastoma (3 papers, 2013 to 2025). The most malignant astrocytic tumor (WHO grade IV). "Analysis of adenosine receptors showed that expression of ADORA2A/A2AR and ADORA2B/A2BR in glioblastoma and diffuse glioma were moderate compared to that of other cancers, while ADORA1/A1R and ADORA3/A3R were expressed at significantly higher levels in glioblastoma compared to all other tumor types." (PMID 35973991, 2022). "Additionally, it has been reported that deletion of ADORA1 leads to an increase in glioblastoma tumor growth, however this observed effect was believed to be mediated through tumor-adjacent microglia." (PMID 24252460, 2013).
hepatocellular carcinoma (3 papers, 2022 to 2025). A malignant tumor that arises from hepatocytes. "In hepatocellular carcinoma cells, ADORA1 increased the tumor proliferation and invasion ability, and a high ADORA1 expression predicted a poor survival rate in patients." (PMID 36290882, 2022). "Hence, we investigated how ADORA1 contributes to ethanol metabolism, using HepG2 human hepatoma cell lines and ADORA1 knockout mice." (PMID 38419509, 2024).
lung carcinoma (3 papers, 2022 to 2025). "Finally, several genes, such as ADRA2A, P2RY12, ADORA1, CXCR1, and CXCR4, were predicted as potential druggable genes for ALI with GGPPS1-knockout, and were associated with the prognosis of lung cancers." (PMID 35795000, 2022).
ovarian carcinoma (3 papers, 2021 to 2025). A malignant neoplasm originating from the surface ovarian epithelium. "Studies suggest that high ADORA1 expression is associated with poorer OS in ovarian cancer patients." (PMID 41465326, 2025). "The ADORA1 gene, which encodes the adenosine A1 receptor, has been investigated for its role in the prognosis of ovarian cancer." (PMID 41465326, 2025). "Moreover, we found that the expression of apoptosis-related genes ras association domain family member 5 (RASSF5) and adenosine A1 receptor (ADORA1) could be modulated by OIN1 in ovarian cancer." (PMID 34681900, 2021). "Moreover, candidate apoptosis- or cell proliferation-related genes RASSF5 and ADORA1 were identified as OIN1 downstream genes in ovarian cancer." (PMID 34681900, 2021). "Taken together, we proposed that OIN1 negatively modulates expression of RASSF5 or ADORA1, which may contribute to the alteration of ovarian cancer cell proliferation." (PMID 34681900, 2021). "A question remains how OIN1 modulates the expression of RASSF5 and ADORA1 in ovarian cancer." (PMID 34681900, 2021). "Notably, treatment with the ADORA1 antagonist SLV320 partially rescued the adenosine-mediated decrease in A2780 cell survival, suggesting that ADORA1 may play a tumor-suppressive role in ovarian cancer." (PMID 34681900, 2021). "Notably, RNA sequencing showed that OIN1 expression was negatively correlated with the expression of apoptosis-related genes ras association domain family member 5 (RASSF5) and adenosine A1 receptor (ADORA1), which were upregulated by OIN1 knockdown in ovarian cancer cells." (PMID 34681900, 2021). "siRNA-mediated OIN1 silencing significantly decreased the in vivo tumor formation of ovarian cancer cells, along with the upregulation of RASSF5 and ADORA1." (PMID 34681900, 2021). "ADORA1 may modulate OIN1-mediated apoptosis in ovarian cancer, making it a possible molecular target for ovarian cancer treatment." (PMID 37337170, 2023).
Arrhythmia (2 papers, 2010 to 2021). Any cardiac rhythm other than the normal sinus rhythm. "PRP can interfere with arrhythmia by regulating the protein level of ADORA1 and the metabolic levels of adenosine and cGMP in the cGMP-PKG pathway." (PMID 34393777, 2021). "Side effects are related to plasma concentrations and include nausea, vomiting and headaches due to PDE inhibition and at higher concentrations to cardiac arrhythmias and seizures due to adenosine A1-receptor antagonism." (PMID 27713276, 2010). "Therefore, we highlight the finding that PRP can significantly restore the high gene expression of ADORA1 and thereby play a role in the treatment of arrhythmia." (PMID 34393777, 2021). "By upregulating the expression of the ADORA1 protein and the levels of adenosine and cGMP metabolites in the cGMP-PKG signalling pathway, PRP can participate in ameliorating arrhythmia." (PMID 34393777, 2021).
Cachexia (2 papers, 2017 to 2020). Severe weight loss, wasting of muscle, loss of appetite, and general debility related to a chronic disease. "Genes for both PTGDS and ADORA1 tended to be up‐regulated in association with cachexia, suggesting increased production of prostaglandin D2 that exerted antilipolytic effect, in concert with ADORA1 stimulation." (PMID 33084249, 2020).
Cognitive impairment (2 papers, 2020 to 2024). Abnormal cognition is characterized by deficits in thinking, reasoning, or remembering. "Three intersecting targets—ACE, MAOA, and ADORA1—were identified as potential targets for caffeine in treating cognitive impairment under high‐altitude conditions, consistent with previous research." (PMID 39670604, 2024). "The conventional adenosine A1 receptor gene (A1R) knockout mice and the A1R agonist CCPA- or antagonist DPCPX-administrated mice were utilized to determine the precise function of A1R signaling in the process of OSAHS-relevant cognitive impairment." (PMID 32733207, 2020).
colon cancer (2 papers, 2013 to 2021). "In colon cancer cells, adenosine, via ADORA1, induces apoptosis by activating caspases." (PMID 24252460, 2013).
Hepatic fibrosis (2 papers, 2014 to 2021). The presence of excessive fibrous connective tissue in the liver. "This is consistent with recent reports showing that antagonism of adenosine A2a receptor prevents and reverses liver fibrosis and antagonism of adenosine A1 receptor reduces mortality of cirrhotic rats." (PMID 24651845, 2014). "In addition, up-regulation of genes involved in tissue injury and hepatic fibrosis (Adora1), caspase-dependent apoptosis (Moap1), and oxidative stress and antioxidant defense (Ephx2 and Oxr1) was identified only in the liver treated with Zn ions." (PMID 33567653, 2021).
Hepatic steatosis (2 papers, 2022 to 2023). Steatosis is a term used to denote lipid accumulation within hepatocytes. "Both mice fed the HFD diet and patients with hepatic steatosis showed increased hepatic ADORA1 expression." (PMID 36278175, 2022). "Specific inhibition of ADORA1 in the liver helps prevent body weight gain and alleviate hepatic steatosis." (PMID 36278175, 2022). "Therefore, we speculated that MLF might regulate lipid metabolism and alleviate hepatic steatosis by modulating the expression of ADORA1." (PMID 36278175, 2022).
Insulin resistance (2 papers, 2021 to 2022). Increased resistance towards insulin, that is, diminished effectiveness of insulin in reducing blood glucose levels. "Our verified experiments in human L02 hepatocytes revealed that the expression levels of ADORA1 genes were upregulated in insulin resistance, while morusin treatment markedly increased cellular glucose consumption stimulated by insulin and downregulated ADORA1 expression." (PMID 36278175, 2022). "Additionally, morusin plays a role in amending insulin resistance of hepatocytes by repressing the expression of the ADORA1 and PPARG genes." (PMID 36278175, 2022). "Additionally, we validated the hypoglycemic effects of morusin on repressing the expression of the ADORA1 and PPARG genes to improve insulin resistance in L02 cells." (PMID 36278175, 2022).
ischemia (2 papers, 2012 to 2017). A hypoperfusion of the BLOOD through an organ or tissue caused by a PATHOLOGIC CONSTRICTION or obstruction of its BLOOD VESSELS, or an absence of BLOOD CIRCULATION. "Thus, for example, adenosine A1 receptor blockade during acute asphyxia in near-term fetal sheep, or ischemia in adult rats was associated with delayed onset of EEG suppression, followed by more rapid onset of cortical depolarization and greater neural injury." (PMID 22720088, 2012).